IL19 (interleukin 19)
Description:
Cytokine that functions as an anti-inflammatory and proangiogenic factor. Polarizes adaptive immunity to an anti-inflammatory phenotype through induction of T-helper 2 responses by both down-regulation of IFN-gamma and up-regulation of IL4 and IL13. Produced by osteocytes, stimulates granulopoiesis and neutrophil formation (By similarity). Exerts its biological effect through a receptor complex consisting of a heterodimer of IL20RA and IL20RB. In turn, activates the Janus kinase (JAK) and signal transducer and activator of transcription (STAT) pathway, and importantly, STAT3.
Synonyms: IL-19; ZMDA1; MDA1; IL-10C; NG.1
Tractability: Antibody: its Gene Ontology location is reachable by antibodies, with high confidence; UniProt places it where antibodies can reach, with medium confidence; UniProt predicts a signal peptide or a membrane-spanning region.
Safety:
Unwanted effects reported when the protein is acted on. In parentheses: how it was acted on, where the effect was seen, and who reports it.
a hypersensitivity reaction to NSAIDs (source: ClinPGx)
Drug Hypersensitivity (source: ClinPGx)
hypersensitivity reaction to NSAIDs (source: ClinPGx)
Gene: Protein-coding gene on chromosome 1 (206,770,764 to 206,842,981, forward strand). Ensembl gene ENSG00000142224.
Subcellular location: Secreted
Pathways (Reactome):
Immune System: Interleukin-20 family signaling
Gene Ontology:
Molecular function: cytokine activity
Biological process: interleukin-19-mediated signaling pathway; immune response; signal transduction; negative regulation of low-density lipoprotein particle clearance
Cellular component: extracellular region
Genetic constraint (gnomAD): Loss-of-function variants: 14 observed, 19.46 expected, observed/expected ratio (o/e) 0.72, 90% interval 0.47 to 1.12. The upper end of that interval is the gene's LOEUF score, 1.12, which puts it in group 4 of 6, group 1 being the genes least tolerant of losing a copy. Missense variants: 160 observed, 183.41 expected, observed/expected ratio (o/e) 0.87, 90% interval 0.77 to 1. Synonymous variants: 61 observed, 66.77 expected, observed/expected ratio (o/e) 0.91, 90% interval 0.74 to 1.13.
Homologues: Orthologues: chimpanzee IL19 (97% identical), macaque IL19 (94% identical), pig IL19 (77% identical), dog IL19 (75% identical), guinea pig IL19 (74% identical), rabbit IL19 (69% identical), mouse Il19 (68% identical), rat Il19 (67% identical), zebrafish il19l (25% identical). Paralogues in human: IL20 (41% identical), IL24 (28% identical), IL10 (19% identical), IL26 (18% identical).
Diseases named in the same sentence as IL19 in open-access papers:
IL19 is named in the same sentence as 152 diseases in open-access papers, as found by Europe PMC text mining. Sharing a sentence is not in itself a finding about the gene and the disease. The quoted sentences say what the papers report.
psoriasis (62 papers, 2006 to 2025). An autoimmune condition characterized by red, well-delineated plaques with silvery scales that are usually on the extensor surfaces and scalp. "Psoriasis is an inflammatory condition that is associated with excessive secretion of proinflammatory cytokines (IL-2, IL-6, IL-8, IL-12, IL-19, IL-22, IL-23, IFN-γ and TNF-α) into blood as well as dermal tissue." (PMID 37266425, 2023). "They introduced Card14ΔE138K/A mutations in mice with psoriasis and found an up-regulation of pro-inflammatory cytokines, IL-23, IL-19, IL-22 and IL-17; chemokines Cxcl1, Ccl20, and Cxcl2; and antimicrobial peptides, Lcn2 and Defb4." (PMID 36012602, 2022). "IL‐19 and IL‐20, members of the IL‐10 family, were found to be associated with psoriasis‐like skin abnormalities and upregulate psoriasis‐related cytokines." (PMID 36245291, 2022). "Confirming that endogenous TWEAK activity had a function in TSLP and IL-19 production in vivo, gene-deficient mice exhibited reduced expression of these molecules in the skin in the AD and psoriasis models, respectively." (PMID 28530223, 2017). "Effective treatment of psoriasis is associated with a decrease in IL-19 level and already within one week of treatment with Etanercept (targeting TNFα signalling) IL-19 expression was rapidly decreased." (PMID 25965695, 2015). "Other cytokines and chemokines associated with psoriasis include IL19, IL20, IL15, and MCP1 (monocyte chemoattractant protein)." (PMID 24069534, 2013). "Overexpression of IL-19 and IL-24 has also been observed in psoriatic skin and both induce keratinocyte hyper-proliferation in a reconstituted human skin model, suggesting a pathogenic role in psoriasis." (PMID 34616394, 2021). "Additionally, IL-19 is linked to both Th2 and Th17 responses, with increased IL19 expression reported in skin lesions of psoriatic patients and elevated IL-19 serum levels correlated with psoriasis severity." (PMID 32886659, 2020). "As KGF signalling probably accounts for the epidermal hyperplasia associated with psoriasis IL-19 activation might play an essential role in maintaining psoriasis plaques." (PMID 25965695, 2015). "Like IL20, IL19 is also associated with psoriasis, another inflammatory disease." (PMID 16959027, 2006). "For instance, IL-36 and IL-17C mainly act synergistically to enhance tissue inflammation; overexpression of IL-20 can lead to epidermal changes characteristic of psoriasis; and IL-19 potentiates the effects of IL-17A via a positive feedback mechanism." (PMID 40303401, 2025). "In psoriasis (PsO), elevated levels of IL-19 have been observed, which induce dysplasia and activation of keratinocytes, and also prompts CD8+ T cells to generate Keratinocyte Growth Factor." (PMID 39104791, 2024). "IL-19 participates in several animal and human diseases, including psoriasis, inflammatory bowel disease, atherogenesis, endotoxic shock, rheumatoid arthritis, and cancer." (PMID 38314821, 2024). "Several other studies have assessed IL-19 concentration levels, and the role of IL-19 in the pathogenesis of other inflammatory skin diseases, such as psoriasis and atopic dermatitis, was established in previous studies." (PMID 38106772, 2023). "Then, to investigate the mechanism of TGF-β induction, we stimulated healthy keratinocytes (NHEK) in vitro with a number of cytokines characterizing the psoriasis microenvironment including IL-1β, IL-6, IL-17A, IL-19, IL-22, IL-23, IL-26, and IFN-γ." (PMID 37391412, 2023). "The anti-inflammatory genetic mediators associated with psoriasis are IL1RN, IL4, IL10, IL13, and IL19." (PMID 37569685, 2023). "Using severity indices for both conditions, they found a significant positive correlation between the serum level of IL-19 and disease severity in both psoriasis and atopic dermatitis." (PMID 38106772, 2023).
psoriasis (continued). "According to our analysis, with the treatment of immunosuppressants in psoriasis, the expression of IL-37 increased gradually, while IL-19, CXCL1, CXCL2, CXCL13 decrease gradually." (PMID 36389813, 2022). "Recently, IL-19 was suggested as an important mediator of the IL-23/IL-17 cascade in psoriasis, and IL-17A-induced expression of IL-19 in keratinocytes amplifies keratinocyte responses via auto-paracrine regulation." (PMID 34616394, 2021). "We evaluated serum levels of IL-17A and other cytokines, including IL-22 and IL-19,18 from the psoriasis molecular signature." (PMID 34643650, 2021). "IL-19 has been considered to be a Th2 cytokine that promotes Th2-skewed diseases such as asthma, atopic dermatitis, psoriasis, and rheumatoid arthritis, however, IL-19 often exerts controversial effects depending on species and types of immune cells." (PMID 33776998, 2021). "IL-19, along with other IL-20 subfamily cytokines such as IL-20 and IL-24, is induced by IL-17A and contributes especially to epidermal hyperplasia in psoriasis." (PMID 34616394, 2021). "In the present study, we showed that IL-10 neutralization enhanced skin inflammation, thickness and scaling in the IMQ-induced psoriasis mouse model beyond day 5, via upregulation of the IL-17/IL-19 axis." (PMID 34616394, 2021). "In vitro assays with human skin fibroblasts from patients with psoriasis and healthy skin were performed to evaluate the direct induction of IL-19 by IL-17." (PMID 34616394, 2021). "Interleukin-19, a member of the IL-20 subfamily together with IL-20 and IL-24, is up-regulated in psoriatic lesions and contributes to keratinocytes hyperplasia in psoriasis." (PMID 34616394, 2021). "In fact, IL-19 plays a critical role in development of various autoimmune diseases, including asthma, psoriasis, inflammatory bowel disease, rheumatoid arthritis, and Type I diabetes." (PMID 33776998, 2021). "Significant upregulation of IL-17A, IL-19, IL-24, and Ki-67 in psoriasis was confirmed in another independent dataset." (PMID 34616394, 2021). "IL-19 has been proposed as a member of the inflammatory IL-23A/IL-17A cascade in psoriasis; its upregulation in keratinocytes is driven by IL-17A, and it acts in an autocrine fashion on keratinocytes to amplify the effects of IL-17A." (PMID 31964744, 2020). "IL-19 is produced by monocytes and epithelial cells and is also strongly upregulated in the keratinocytes of psoriasis patients." (PMID 31964744, 2020). "We also demonstrate that our IL-19 assay has similar applicability for psoriasis patients treated with tumor necrosis factor (TNF)α inhibitors such as etanercept, or Janus associated kinase (JAK) 1/2 inhibitors such as baricitinib." (PMID 30914699, 2019). "In this study, we developed a sensitive and specific novel immunoassay for IL-19 to reveal that baseline circulating IL-19 levels correlate with skin involvement in psoriasis." (PMID 30914699, 2019). "Serum IL-19 levels, at baseline and endpoint, in patients with psoriasis were again highly correlated with PASI (Spearman’s r = 0.74, p < 0.0001)." (PMID 30914699, 2019). "Following these results, we measured IL-19 in genital psoriasis patients enrolled in a phase 3b ixekizumab trial at baseline and after 2, 4, and 12 weeks of treatment with placebo or ixekizumab (160 mg loading dose followed by 80 mg Q2W)." (PMID 30914699, 2019). "Next, we measured IL-19 levels in patients with psoriasis in a phase 2 trial (investigating the JAK1/2 inhibitor baricitinib) at baseline and after 12 weeks of treatment with placebo or various doses of baricitinib and compared IL-19 levels with PASI scores." (PMID 30914699, 2019). "In contrast, serum IL-19 concentrations measured in baseline samples from patients with psoriasis enrolled in a phase 2 ixekizumab psoriasis study were markedly elevated (geometric mean of 87 pg/mL, p < 0.0001)." (PMID 30914699, 2019).
psoriasis (continued). "In baricitinib- and etanercept-treated psoriasis patients, IL-19 decreases also correlated with improvement." (PMID 30914699, 2019). "In psoriasis patients, IL-19 increased prior to skin relapse when treatment with ixekizumab was discontinued; and decreased again after re-treatment." (PMID 30914699, 2019). "Upon treatment of psoriasis, genital psoriasis, and psoriatic arthritis patients with ixekizumab, serum IL-19 decreased prior to PASI improvement." (PMID 30914699, 2019). "This novel IL-19 biomarker assay allowed us to demonstrate for the first time that decreases in serum IL-19 levels precede clinical responses in psoriasis when the therapeutic anti-IL-17A antibody ixekizumab is administered." (PMID 30914699, 2019). "Not only was IL-19 increased in psoriasis and correlated to PASI, but ixekizumab administration led to rapid, sustained IL-19 decreases to normal levels, with decreases at 2-weeks correlating with PASI improvement at 16-weeks." (PMID 30914699, 2019). "Serum IL-19 levels were measured in patients with psoriasis enrolled in a phase 3 ixekizumab study (UNCOVER-2), which included an etanercept active comparator arm." (PMID 30914699, 2019). "We next measured IL-19 concentrations in phase 2 psoriasis patients at baseline and after 16 weeks of treatment with placebo or various doses of ixekizumab and compared the results with PASI scores." (PMID 30914699, 2019). "Overexpression of Il20, Il22 or Il24 in mice leads to the development of psoriasis-like skin lesions, and levels of IL-19, IL-20, IL-22 and IL-24 are increased in psoriatic skin." (PMID 27799070, 2016). "Polymorphism in the genes coding for IL-19, IL-20 and LTA (lymphotoxin alpha) have been associated with both PPP and psoriasis." (PMID 27152848, 2016). "Quantitative PCR confirmed a resveratrol dependent decrease in mRNA levels of IL-17A and IL-19; both central in developing psoriasis." (PMID 25965695, 2015). "Previous studies showed that IL-19 contributes to the pathogenesis of autoimmune diseases such as psoriasis, asthma, and rheumatoid arthritis by upregulation of pro-inflammatory cytokines, including IL-6 and TNF-α." (PMID 25794104, 2015). "In some respects, the strongest evidence from our study supports the IL-20 family cytokines as drivers of differential gene expression in psoriasis (i.e., IL-19, IL-20 and IL-24)." (PMID 23915137, 2013). "Of note, the haplotype in IL19 and IL20 exhibited a susceptibility factor for the development of psoriasis." (PMID 24069534, 2013). "IL-24 expression is increased in inflammatory skin disease like AD or psoriasis and IL-24 induces, as well as the other IL-10 family members IL-19 and IL-20, the proliferation of keratinocytes in 2D cultures." (PMID 23531535, 2013). "Expression of IL-19, IL20Rα, and IL20Rβ can be detected in psoriatic lesions, and treatment of psoriasis reduces expression of IL-19." (PMID 22844641, 2012). "A putative role for IL-19 has been put forth in the development of psoriasis, a chronic inflammatory skin condition characterized by increased proliferation of keratinocytes leading to the development of plaque-like epidermal lesions." (PMID 22844641, 2012). "Notably, IL-19 and IL-20 are overexpressed in the basal and suprabasal layers of psoriatic keratinocytes, although their circulating levels in the serum of psoriasis patients are reduced when compared to healthy controls." (PMID 40731810, 2025). "Moreover, IL-17A principally drives the expression of four key cytokines: IL-36, IL-17C, IL-20, and IL-19, each possessing distinct functions in psoriasis." (PMID 40303401, 2025). "In addition, mRNA decreased for both interleukin 17A (IL-17A) and interleukin 19 (IL-19), which are crucial in developing psoriasis." (PMID 38001807, 2023). "Not much is known about the function of the IL-19, IL-20, and IL-24 cytokines and their receptors, which are intrinsic to keratinocytes and are mostly associated with autoimmunity in psoriasis." (PMID 36225230, 2022).
psoriasis (continued). "In addition, an ex vivo human psoriasis skin co-culture system was used to examine the effects of biologics targeting IL-17A on IL-19 expression." (PMID 34616394, 2021). "IL-19 may also be applicable as an assessment tool in scabies, as suggested for psoriasis and atopic dermatitis patients." (PMID 34925353, 2021). "Additionally, genes known for their role in psoriasis and atopic dermatitis were upregulated, e.g., IL-19." (PMID 34925353, 2021). "Abatacept did not maintain suppression of the pathogenic IL-23-mediated psoriasis molecular signature in lesions after ustekinumab withdrawal, and serum IL-19 levels increased." (PMID 34643650, 2021). "Our findings indicate that a serum IL-19 assay for disease activity could provide to clinicians managing psoriasis patients an important tool to complement the therapeutic advances being made in treating this chronic, immune-mediated, skin disease." (PMID 30914699, 2019). "Using this assay, we show that IL-19 levels are dramatically elevated in psoriasis, genital psoriasis, and psoriatic arthritis, are highly correlated with skin involvement, and function as a leading indicator of skin disease severity during treatment with multiple classes of medications." (PMID 30914699, 2019). "Therefore, measurement of serum IL-19 provides clinicians with an objective disease-activity assessment tool for psoriasis and atopic dermatitis patients." (PMID 30914699, 2019). "In contemplating IL-19 as a biomarker for psoriasis, atopic dermatitis, and possibly other epithelial diseases, we recognized the importance of cellular cross-talk between bone-marrow-derived myeloid cells and epidermal keratinocytes, both of which can produce IL-19." (PMID 30914699, 2019). "Our novel interleukin-19 (IL-19) immunoassay was initially tested to determine concentrations of IL-19 serum levels, then correlated with the psoriasis activity and severity index (PASI) in psoriasis, and the eczema area and severity index (EASI) in atopic dermatitis." (PMID 30914699, 2019). "After obtaining these results in psoriasis patients, we next measured IL-19 concentrations in patients with psoriatic arthritis enrolled in the phase 3 ixekizumab trial, SPIRIT-P1, at baseline and after 12 weeks of treatment with ixekizumab and compared the results with PASI scores." (PMID 30914699, 2019). "In light of our findings, we contemplated the mechanisms that could account for the potential role of IL-19 as a biomarker for psoriasis, atopic dermatitis, and possibly other epithelial-based diseases." (PMID 30914699, 2019). "Reliable quantitation of circulating IL-19 may provide healthcare professionals with an objective, biochemical assessment for evaluating disease activity in psoriasis patients that avoids inter-observer variability from visual examinations." (PMID 30914699, 2019). "In line with this, single-nucleotide polymorphisms of the IL-19 gene (but not the IL-20 or IL-24 genes) are protective in psoriasis." (PMID 30319661, 2018). "In addition, IL-19 and IL-17 are known to induce other interleukins which contributes to the psoriasis typical epidermal alterations." (PMID 29867905, 2018). "The effect of the concurrent presence of IL-17 and IL-19 in psoriasis lesions might have impact on various levels of the pathogenic progression." (PMID 29867905, 2018). "We also uncovered “psoriasis response elements” (PREs) overrepresented in psoriasis DEG promoter regions, which are present within enhancers near cytokine-encoding genes (e.g., IL17A, IL19 and IL1B)." (PMID 25883770, 2015). "Our study also supports the notion that non-lesional skin of psoriasis patients is diseased skin, as some important psoriasis genes, such as IL-22, IL-19 and LCN2, were differentially expressed between thick and thin plaque psoriasis only within non-lesional skin." (PMID 26176783, 2015).